RNU6-1291P (RNA, U6 small nuclear 1291, pseudogene)
Gene: Small nuclear RNA gene on chromosome 14 (51,522,864 to 51,522,967, forward strand). Ensembl gene ENSG00000252400.
Homologues: Orthologues: chimpanzee U6 (100% identical), rabbit U6 (58% identical), pig U6 (57% identical), rat LOC120103219 (55% identical), guinea pig U6 (54% identical), dog RNU6-1291P (53% identical), pig U6 (52% identical), guinea pig U6 (51% identical), mouse Gm54640 (51% identical). Paralogues in human: RNU6-1011P (76% identical), RNU6-1117P (76% identical), RNU6-242P (76% identical), RNU6-946P (76% identical), RNU6-1237P (75% identical), RNU6-647P (75% identical), RNU6-658P (75% identical), RNU6-1124P (74% identical), RNU6-1164P (74% identical), RNU6-1251P (74% identical), RNU6-38P (74% identical), RNU6-47P (74% identical), and 1287 more.